CXCR5 (C-X-C motif chemokine receptor 5)
Diseases named in the same sentence as CXCR5 in open-access papers (continued):
Sharing a sentence is not in itself a finding about the gene and the disease.
infection (continued). "Moreover, in Hodgkin’s lymphoma, genetic analysis determined that CXCR5+ ICOS+ CD8+ T cells are most closely related to CD4-derived Tfh than other cell populations, and thus these cells may undergo similar metabolic alterations under conditions of infection." (PMID 35493515, 2022). "Moreover, so-called recently activated CXCR5+CD4 T cells, identifiable by upregulation of programmed-death receptor-1 (PD1), Ki-67 protein (Ki-67) and ICOS expression, appear in blood in response to specific immune activation post vaccination or during infection." (PMID 34446066, 2021). "Furthermore, SjS patients with either serological evidence of past EBV infection or recent infection/reactivation presented higher values of CXCR3+ CD4+ T cells (Th1) and CXCR3+ CXCR5+ CD4+ T cells (Tfh1) compared to those without serological evidence of active infection." (PMID 33603079, 2021). "Therefore, levels of CXCR3 (receptor for CXCL9 and CXCL10), CXCR5 (receptor for CXCL13), CCR5 (receptor for CCL3 and CCL5), and CCR7 (receptor for CCL19) were analyzed on CD45hiCD11bloCD19+ B cells which infiltrated the brain at 7, 14, 30, and 60 days post infection." (PMID 27207308, 2016). "In contrast, in mice infected with the LCMV Armstrong strain having cleared the infection, GP33-specific memory CD8+ T cells did not express CXCR5." (PMID 37122741, 2023). "CXCR5+TIM-3+ cells only increased at 30 and 60 days of infection in dLNs, whereas no increase was observed in the lesions." (PMID 37691941, 2023). "In support, studies have shown that CXCR5-expressing CD8+ T cells are found predominantly in secondary lymphoid organs, while terminally-differentiated cells are localized in major infection sites, including lymphoid and non-lymphoid tissues." (PMID 37691941, 2023). "Of note, very few CXCR5+PD-1+CD8+ T cells were detected in Stat5fl/−CD8Cre/YFP and control mice without infection." (PMID 31562329, 2019). "Interestingly, in late phases >day 20 of LCMV-c13 infection B cells do not appear to be absolutely required for the development of CXCR5+ cells, suggesting other types of antigen presenting cells could contribute to the sustained TFH response as this does not occur in MHCII KO." (PMID 29734372, 2018). "Prior to day 6 post-infection, for example, Icos−/− CD4+ T cells were not defective in their ability to express the canonical Tfh cell markers Bcl6, PD-1, CXCR5, or IL-21." (PMID 27559335, 2016). "While IL-21 and CXCR5, widely considered Tfh-related molecules, are both predominantly expressed by IFN-γ+ cells in this infection, this population is not regulated by Bcl6." (PMID 26646149, 2015). "A more detailed analysis at day 10 of a primary or secondary infection (data not shown), which revealed a distinct shift in the expression of CD19, MHC class II, CXCR4 and CXCR5 between splenic B220+ cells and CD138+ cells in spleen, blood and bone marrow." (PMID 21124900, 2010). "As expected from the short interval spanning between infection and sample collection, the maternal frequency of B cells, class-switched IgD– B cells, CD4+ T cells, activated CD4+ T cells, CCR6+ T cells, and CXCR5+ T cells remained equivalent in the presence or absence of symptoms." (PMID 37490342, 2023). "We found that the frequency of CXCR5+CD40L+ cells tends to increase significantly (p < 0.05 for both spike and non-spike), while CXCR5+PD1+ helper T cells tend to decrease, though not significantly, after 1 month of infection." (PMID 36248882, 2022). "We found that the majority of CD11b+ LyChi Ly6G- CD64+ inflammatory monocytes present in the ear of VACV-infected mice at 5 days post-infection were CCR5+, the receptor for CCL4, rather than CCR2+, or positive for the receptors for CXCL13 (CXCR5) or CXCL9 and CXCL10 (CXCR3)." (PMID 31603920, 2019).
infection (continued). "Flow cytometry analysis revealed that, although conventional CD4+ T cells gradually express CXCR5, PD-1, Bcl6, and SLAM and produce high levels of IL-21 after infection, TCRβ+CD1d-tetramer+ NKT cells do not upregulate Bcl6, CXCR5, or PD-1 and express moderate levels of SLAM and IL-21." (PMID 29249358, 2018). "Similarly, the absence of OX40 does not affect the expression of CXCR5 on antigen-specific CD4+ T cells and the development of IgG1 responses after infection with the rodent roundworm Heligmosomoides polygyrus." (PMID 30405612, 2018).
cancer (123 papers, 2008 to 2026). A tumor composed of atypical neoplastic, often pleomorphic cells that invade other tissues. "CCL3 on CD8+ T cells was also predicted to interact with CCR1 or CCR5 on myeloid cells and CXCL13 on CD8+ T cells was predicted to interact with CXCR5 on B cells or ACKR4 on cancer-associated fibroblasts." (PMID 39478117, 2024). "In this review, we summarize the molecular events and TME alterations caused by CXCL13/CXCR5 and briefly discuss the potentials of agents targeting this axis in different malignant tumors." (PMID 34947813, 2021). "In this study, we found low expression mRNAs/lncRNAs were significantly associated with cancer patients’ better overall survival and high expression mRNAs were significantly associated with cancer patients’ worse overall survival except for CXCR5 and HPN-AS1." (PMID 34220926, 2021). "Intriguingly, utilizing intrakine CXCL13-KDEL, which traps CXCR5 in the endoplasmic reticulum, causes a prolonged growth arrest of cancer cells." (PMID 34947813, 2021). "Signaling via the CMS1-associated CXCL13, and its receptor CXCR5, has been shown to induce cancer progression through PI3K, Akt, ERK 1/2, and Jun." (PMID 34830978, 2021). "Based on the single‐cell sequencing derived from NPC clinical samples, RANBP17 is expressed in EBV‐associated NPC cells, KCNJ10 is detectable in myeloid cells, and CXCR5 is dormantly expressed by B cells, while cancer‐associated fibroblasts mainly express CCL19 and CCL21." (PMID 41397929, 2025). "CXCR5 has been implicated in tumorigenesis and cancer progression." (PMID 40091778, 2025). "Importantly, the key effector cells of the CXCL13/CXCR5-associated immune axis express PD-1, hence attracting increasing interest as secondary or ancillary targets of anti-PD-1 therapy in different cancer types." (PMID 36836910, 2023). "CXCL13, a chemokine ligand for CXCR5 that is associated with B-cell recruitment, may be involved in cancer progression and has been shown to be overexpressed in oral SCC37,38." (PMID 33888854, 2021). "A cancer microenvironment enriched with CXCL13 elicits the recruitment of CXCR5-expressing leukocytes." (PMID 40548381, 2025). "The CXCL13/CXCR5 axis was reported to be involved in regulating cancer cell migration and shaping an immunosuppressive TME, highlighting its potential as a prognostic biomarker and therapeutic target." (PMID 40943634, 2025). "CXCR5 was the specific receptor of CXCL13, and the CXCL13-CXCR5 axis was proved to be activated in carcinogenesis, development, and metastasis in various malignant tumors and differentiation of immune cells." (PMID 38880863, 2024). "Previous studies demonstrated that the B-cell chemoattractant CXCL13 was recently found to be associated with the CXCR5+ T follicular helper cell (TFH cell) infiltration and improved survival in human cancer." (PMID 39001456, 2024). "Among the pivotal chemotactic factors, CXCL13 and CXCR5 assume critical roles in shaping the biology of cancer cells." (PMID 38459390, 2024). "CXCL13 is a signaling molecule that binds to its receptor, CXCR5, and is known to be involved in several cancer‐related pathways." (PMID 39344390, 2024). "The Tfh cell markers PDCD1 and CXCR5 were decreased during the carcinoma progression, which is consistent with the change of t peripheral Tfh population." (PMID 38343544, 2024). "Inhibitor targeting the CXCL13/CXCR5 axis was demonstrated to have an encouraging effect on cancer treatment." (PMID 36816030, 2023). "Aberrantly active CXCL13/CXCR5 signaling promotes cancer cell growth through complex molecular mechanisms in breast, intestinal, and lung cancers." (PMID 37503314, 2023). "The overexpression of CXCR5 and its cognate ligand CXCL13 has been implicated in many different types of cancer." (PMID 35978426, 2022). "The CCL4/CCR5 axis, CXCL9/CXCR3-axis, and CXCL13/CXCR5-axis have previously been shown to promote cancer progression and metastasis." (PMID 36163179, 2022).
cancer (continued). "CXCL13 and its chemokine receptor 5 (CXCR5) are among the key chemotactic factors which play crucial roles in deriving cancer cell biology." (PMID 35432485, 2022). "CD8+ and CD4+ T cells, cancer-associated fibroblasts, cancer cells, and dendritic cells are able to secrete CXCL13, and CD8+ and CD4+ T cells, B cells, and cancer cells express CXCR5." (PMID 35053457, 2022). "CXCL13/CXCR5 signaling axis modulated cancer cell ability to grow, proliferate, invade, and metastasize." (PMID 36032660, 2022). "Because of cancer heterogeneity, identifying CXCR5+CD8 T cells requires a robust screen across multiple cancer types to enable a sound and clear prognostic value for using CXCR5+CD8 T cells as a biomarker or immune cell therapy target." (PMID 36314014, 2022). "The PD-1+ TILs that secreted CXCL13 and avidly interacted with CXCR5+PD-L1+ cancer cells were predominant in controls." (PMID 35392977, 2022). "We also summarize recent preclinical and clinical evidence regarding the ICI-therapeutic implications of targeting the CXCL13/CXCR5 axis and discuss the potential role of this signaling pathway in cancer immunotherapy." (PMID 35053457, 2022). "This mini-review focuses on CXCR5+CD8 T cells in cancer, and implications for immune-mediated adverse event (IMAEs) development in patient immunotherapy treatments." (PMID 36314014, 2022). "The CXCL13/CXCR5 signal axis plays a vital role in the occurrence and development of several human cancers." (PMID 35898471, 2022). "CXCL13 and its homologous receptor CXCR5 have demonstrated outstanding abilities to regulate tumor growth, and play crucial roles in inflammation, cancer, and immune responses." (PMID 36238299, 2022). "CXCR4 and CXCR5 have been recognized as essential players in cancer biology, with the CXCL12/CXCR4 axis playing a pivotal role in inducing metastases." (PMID 35456016, 2022). "T cells follicular helper, characterized by the expression of CXC chemokine receptor 5 (CXCR5), are positively connected with survival of cancer patients by the immunoprotective functions of CXCL13 which is correlated with CXCR5 in germinal center." (PMID 36397112, 2022). "CXCR5+CD8 T cell heterogeneity also exists within cancer and complicates our use of therapies directed at CD8 T effectors." (PMID 36314014, 2022). "In vitro experiments showed that CXCR5 overexpression reversed the inhibitory effect of matrine on invasion and apoptosis to promote cancer progression." (PMID 36238299, 2022). "CXCR5+CD8 T cells appear functional with effector/cytolytic capacity in cancer despite high PD-1 expression." (PMID 36314014, 2022). "The role of the chemokine CXCL13 and its receptor, C-X-C chemokine receptor type 5 (CXCR5), has been reported to be a major factor in the progression of many cancers, including PC." (PMID 35335890, 2022). "Chemokine receptor signaling was of interest, and we found CXCR4 and CXCR5 comentioned with GPRC5C in a review of vascular development dysregulation relevant to cancer." (PMID 34007962, 2021). "And these results were in accordance with the previous studies, which revealed that CXCR5 participated in the progression and poor prognosis in many types of cancers." (PMID 34114971, 2021). "CXC chemokine ligand‐13 and its corresponding receptor CXCR5 have been widely reported in various cancers." (PMID 34427969, 2021). "The CXCL13 and chemokine receptor 5 (CXCR5) signaling axis has a key role in the occurrence and development of several human cancers." (PMID 33579281, 2021). "Next, we observed significant associations of the expression levels of CD20 with CCR6 (total rho=0.62), CCR7 (total rho=0.79), and CXCR5 (total rho=0.73) in most cancer types." (PMID 35069521, 2021). "CXCL13 and CXCR5 have important roles in cancer and represent potential markers to predict the response to immune checkpoint therapy." (PMID 34947813, 2021).
cancer (continued). "Increasing evidence revealed that CXCR5 was highly expressed in many human cancers and was related to occurrence, invasion and metastasis of tumors." (PMID 34114971, 2021). "The role of the CXCL13/CXCR5 pathway in the cancer stem cells of other malignancies remains to be investigated." (PMID 34947813, 2021). "The findings revealed that there was a substantial difference in CXCR5 staining between cancer and surrounding normal tissues." (PMID 34922542, 2021). "It has been widely reported that the CXCL13/CXCR5 axis activates the canonical NFκB pathway and amplifies inflammatory responses in several cancer cells." (PMID 33213490, 2020). "To summarize, CXCL13 and its receptor CXCR5 have emerged as key players of cancer initiation and progression." (PMID 31354634, 2019). "New discoveries in the CXCL13:CXCR5 field would also aid clinical decision-making for cancer patients, bringing us closer to the promise of translational precision medicine." (PMID 31354634, 2019). "CXCL13:CXCR5 axis is involved in many biological responses in immune cells as well as in cancer cells, as described in subsequent sections." (PMID 31354634, 2019). "Future studies to evaluate the in vivo efficacy of CAR/CXCR5 immunotherapy must address multiple complexities under active study in the cancer field, plus others distinct for HIV." (PMID 29616024, 2018). "This view is also supported by a recent study demonstrating a growth advantage of CXCR5-positive cancer cells within the liver of mice presumably through CXCL13 produced by liver cells in their microenvironment." (PMID 18781150, 2008). "CXCR5 has previously been employed to increase CAR-T cell infiltration into CXCL13+ cancers." (PMID 39450160, 2024). "The pro-cancer and anti-cancer effects of CXCL13-CXCR5 axis on NSCLC still remain to be studied, and some scholars have pointed out that it is a poor prognostic factor for immunotherapy because of the presence of PD-1 on the surface of CXCL13+ T cells and CXCR5+ T cells." (PMID 38124739, 2023). "Moreover, compared to those obtained from the circulation of the cancer patients, the lymph node‐derived PD‐1+CXCR5+ cytotoxic T cells displayed considerable capacities to secrete TNF‐α and especially IFN‐γ." (PMID 38069525, 2023). "When the PD-1/PD-L1 signal was inhibited, CXCL13 produced by ASPH+ cancer cells recruited CXCR5+/CD8+ T lymphocytes to tertiary lymphoid structures (TLSs), comprising effector and memory CTLs, T follicular helper cells, B cell germinal center, and follicular dendritic cells." (PMID 35392977, 2022). "In this review, therefore, we discuss the CXCL13/CXCR5 axis and summarize its mechanism of action in cancer cells and lymphocytes, its contributions to immunity and cancer pathobiology, and its role in response to immunotherapy and potential to serve as a biomarker." (PMID 35053457, 2022). "These CTLs secreted CXCL13 to recruit more CXCR5+ immune cells and to lyse CXCR5+ cancer cells." (PMID 35392977, 2022). "However, gene knockdown evidence including the neutralization of overexpressed CXCL13 or CXCR5 activities has displayed the therapeutic potential of this important chemokine axis in numerous cancers." (PMID 36217194, 2022). "Simultaneously, CXCL13 derived from cancer cells binding CXCR5 on T cells may enhance PD1/PD-L1 mediated exhaustion resulting in apoptosis of effector lymphocytes." (PMID 35392977, 2022). "As a specific receptor of CXCL13, CXCR5 mediates cancer functions regulated by CXCL13." (PMID 35978426, 2022). "This review aims to provide an overview of the CXCL13/CXCR5 signaling axis to summarize its mechanisms of action in cancer cells and lymphocytes, in addition to effects on immunity and cancer pathobiology, and its potential as a biomarker for the response to cancer immunotherapy." (PMID 35053457, 2022). "In summary, the CXCL13/CXCR5 signaling in T cells, B cells, and cancer cells are similar." (PMID 35053457, 2022).